UCA1 (urothelial cancer associated 1)
Diseases named in the same sentence as UCA1 in open-access papers (continued):
Sharing a sentence is not in itself a finding about the gene and the disease.
cancer (continued). "In addition, NEAT1, UCA1, HIF1A-AS1, and Evf2 also interact with core subunits of SWI/SNF complexes in a similar manner in various cancer types." (PMID 28634418, 2017). "UCA1 was originally reported to be largely restricted to embryonic tissues and cancers and not to be expressed in normal bladder tissue, but it is clearly detectable by sensitive techniques in benign bladder tissues." (PMID 28430799, 2017). "Various lncRNAs, such as ROR, HOTAIR, H19, UCA1, and ARSR, are involved in cancer stemness." (PMID 29299179, 2017). "Among them, several lncRNAs represent promising noninvasive cancer biomarkers for detection in patient's body fluids, including PCA3, HOTAIR, HULC, MALAT1, H19, LINC00152, RP11-160H22.5, XLOC_014172, LOC149086, AA174084, and UCA1." (PMID 28634418, 2017). "As activation of FGFR1 has been documented to promote EMT in other cancers, it is likely that induction of FGRF1 signalling by UCA1 could promote EMT." (PMID 28430163, 2017). "Indeed, UCA1, PVT1 and H19 can serve as a molecular marker for lymph node metastasis in various cancers." (PMID 28410241, 2017). "UCA1 may serve not only as a molecular marker for LNM, but also as a prognostic factor for patients with various cancers." (PMID 27713161, 2017). "A likely lncRNAs profile will include, among others, HOTAIR, MEG3, NEAT1, UCA1, and/or AK126698 in cancer-drugs cisplatinum-based therapies, and the recently proposed GAS5, UCA1, BC087858 and SOX2-OT involved in the gene-target therapies as EGFR-TKIs based oncological treatments." (PMID 28904641, 2017). "For the thirty-one articles remaining, full text was assessed carefully and 21 were excluded for their insufficient data, or for they focused on the level of UCA1 from other cancers rather than digestive system malignancies." (PMID 28074092, 2016). "Exosomal LINC00265, LINC00467, UCA1, and SNHG1 may act as promising cell-free biomarkers for AML diagnosis and treatment monitoring and provide a new frontier of liquid biopsy for this type of cancer." (PMID 36276083, 2022). "Our observations prove that exosomal LINC00265, LINC00467, UCA1, and SNHG1 may act as novel cell-free indicators for AML diagnosis and treatment monitoring and provide a new frontier of liquid biopsy for this type of cancer." (PMID 36276083, 2022). "Nonetheless, nicotine could promote proliferation of cancer cells through regulation of multifarious genetic pathways, and the expressional change of UCA1 might not reflect all carcinogenic actions of nicotine." (PMID 32143722, 2020). "Currently, a novel study focused on the function of seRNA UCA1-activated YAP, and discovered that aberrant activation of YAP/TAZ (transcriptional coactivator with PDZ-binding domain) axis exists in the microenvironment of various cancers including GC, CRC, lung cancer and breast cancer." (PMID 32278350, 2020). "Notably, several HALs, such as UCA1, PVT1, H19 and MALAT1, might adapt more than one action mode in different cancer types." (PMID 32370770, 2020). "First, the cut-off values of UCA1 high and low expression were lack of uniform standard due to different methods and criteria in different types of cancer, which may result in some heterogeneity and affect the results of the study." (PMID 30918102, 2019). "Furthermore, lncRNA UCA1 is a direct regulator of the PI3K-AKT-mTOR pathway which is often found to be deregulated in human cancers and is known to contribute to chemoresistance of cancer cells." (PMID 29967761, 2018). "First, the criterion of high expression for UCA1 in tissue samples was not the same in different studies, and it was hard to get a consensus cut-off value to define the UCA1 overexpression in various cancers." (PMID 28380443, 2017). "The clinical implications of UCA1 in various cancers have not been studied well." (PMID 27329842, 2016). "However, there is no doubt whether further investigation on the role of UCA1 as a prognostic marker will contribute to the treatment of cancer." (PMID 33777227, 2021).
cancer (continued). "Other malignant tumors are no exception, LncRNA CCAT2 and UCA1 can activate Wnt and promote the development, migration and invasion of BC." (PMID 34135756, 2021). "Considering that Uca1 levels were higher in advanced TSCC, it was hypothesized that its deregulation primarily occurs in cancer progression and not in its initiation." (PMID 29206174, 2017). "Although inhibition of ERK signaling can promote cancer radiosensitization, we did not detect altered ERK 1/2 (T202/Y204, T185/Y187) phosphorylation, and thus this pathway is likely not contributory to UCA1 radiosensitization." (PMID 27902466, 2017). "While these findings suggest that UCA1 may be a useful prognostic marker for HCC, other studies have found elevated plasma levels of this lncRNA in other kinds of cancer, suggesting that it may not be specific for HCC." (PMID 30159431, 2017).
infection (7 papers, 2015 to 2025). The state of being infected such as from the introduction of a foreign agent such as serum, vaccine, antigenic substance or organism. "Our analysis shows increased m6A methylation of GAS5, NORAD, and UCA1 during infection, pointing to further layers of post-transcriptional regulation." (PMID 41267684, 2025). "Especially, several lncRNAs that exhibited transcriptional regulation, such as GAS5, THRIL, MIR155HG, and UCA1, also displayed consistent or increased m6A methylation signals following infection." (PMID 41267684, 2025). "Positive Hepatitis C virus (HCV) infection correlated with elevated LINC00152 expression (p = 0.001) but decreased UCA1 expression (p = 0.05)." (PMID 39609501, 2024). "The results showed that UCA1 elevated with increasing amounts of MOIs and the eminent upregulation was observed from 24 h after infection and onward." (PMID 34345210, 2021). "UCA1 expression was significantly reduced on days 8 and 14 of differentiation after infection of the shRNAs." (PMID 30349036, 2018). "In a similar manner, the number of BGC-823 invading cells decreased after stable infection with lenti-UCA1-siRNA." (PMID 29212166, 2017). "UCA1 was upregulated by approximately 90-fold during wtKSHV infection and approx. 300-fold during Δcluster-KSHV infection." (PMID 28715488, 2017). "UCA1 lenti-UCA1-siRNA stable infection lowered the number of BGC-823 invading cells, as shown by the decrease in the percentages of invasion when compared with the negative control group." (PMID 29212166, 2017). "To do this, we utilized lentivirus infection to deliver short-hairpin RNA targeting UCA1 (shUCA1) alongside a control short-hairpin scramble sequence (shSCR) in our K562 background cell line." (PMID 26053097, 2015). "Furthermore, stable infection with lenti-UCA1-siRNA inhibited the expression of AKT3, p-AKT3, p-mTOR, and S6K, and increased the expression of EIF4E in BGC-823 cells, when compared with blank and negative control cells." (PMID 29212166, 2017). "The Transwell® assay also showed similar results after stable infection with the lenti-UCA1-siRNA." (PMID 29212166, 2017). "The fact that the upregulation observed in transfected cells is much less than in the context of infection could be a consequence of either an altered stoichiometry or absolute expression levels of latency proteins, or mean that other viral genes might contribute to UCA1 upregulation." (PMID 28715488, 2017). "The expressions of lncRNAs UCA1, GAS5, NORAD, BISPR, and NEAT1 were quantified using Illumina cDNA (RNA-seq) sequencing data and compared to dRNA-seq using fold change expression in infection (normalized reads in infected/normalized reads in uninfected)." (PMID 41267684, 2025). "Since UCA1 was upregulated under both infection conditions and its cDNA sequence contained no seed matches for any KSHV miRNAs, UCA1 is presumably not regulated by a miRNA-dependent mechanism." (PMID 28715488, 2017). "The upregulation of UCA1 in patients as opposed to initial single cell type cellular events might also reflect differences in initial infection events as opposed to systemic later stages of infection." (PMID 41267684, 2025).
cardiovascular diseases (5 papers, 2022 to 2025). "Several lncRNA–mRNA regulatory axes are involved in the action mechanisms of MSC-Exos in cardiovascular diseases, such as KLF3-AS1/sirtuin 1 (SIRT1), MALAT1/autophagy-related 4a (ATG4a), urothelial cancer associated 1 (UCA1)-Bcl-2, and Mir9-3hg/Pum2." (PMID 38812041, 2024). "Several studies also investigate the correlation of lnc‐UCA1 with disease severity in cerebro‐cardiovascular disease patients, which may be utilized to monitor disease progression." (PMID 34850451, 2022). "A growing number of researches have manifested that multiple lncRNAs, including lncRNA UCA1, lncRNA TINCR, and lncRNA MIAT, contribute to regulating heart development and cardiovascular disease." (PMID 35703318, 2022). "While few studies report the roles of lnc‐UCA1, miR‐26a, and miR‐195 in cardiovascular disease patients especially in CHD patients, not to mention the intercorrelation between lnc‐UCA1 and miR‐26a and miR‐195 in these patients." (PMID 34850451, 2022).
digestive system cancer (4 papers, 2016 to 2019). A primary or metastatic malignant neoplasm involving any part of the digestive system. "The pooled results of 14 studies indicated that high expression of UCA1 was significantly associated with poorer OS in patients with digestive system cancers (HR: 1.89, 95 % CI: 1.52–2.26)." (PMID 28380443, 2017). "Therefore, we performed this current comprehensive meta-analysis to evaluate the association between UCA1 expression level and prognosis in patients with digestive system cancers." (PMID 28380443, 2017). "The results indicated that a significantly shorter OS was observed in patients with high expression level of UCA1 (HR = 1.71, 95% CI: 1.43–1.99), in the subgroup analysis, the association was also observed in patients with cancers of digestive system (HR = 2.12, 95% CI: 1.59–2.66)." (PMID 27517147, 2016). "Elevated level of UCA1 indicated the poor clinical outcome for patients with digestive system cancers." (PMID 28380443, 2017). "The pooled results of 3 studies indicated a significant association between UCA1 and DFS in patients with digestive system cancers (HR = 2.50; 95 % CI = 1.30–3.69)." (PMID 28380443, 2017). "But clinicopathological value of UCA1 in a specific kind of digestive system cancer was distinctive and even contradictory." (PMID 28380443, 2017). "Nevertheless, the exact molecular mechanisms of UCA1 in carcinogenesis and progression of digestive system cancers was still pending exploration." (PMID 28380443, 2017). "Quantitative meta-analysis was performed with standard statistical methods and the prognostic significance of UCA1 in digestive system cancers was qualified." (PMID 28380443, 2017). "A comprehensive retrieval was performed to search studies evaluating the prognostic value of UCA1 in digestive system cancers." (PMID 28380443, 2017). "This study aimed to clarify the prognostic value of UCA1 in digestive system cancers." (PMID 28380443, 2017). "The expression patterns and biological roles of UCA1 in digestive system cancers was explored." (PMID 28380443, 2017). "The prognostic value of UCA1 in digestive system cancers was assessed." (PMID 28380443, 2017). "However, until now, no specific meta-analysis was reported for assessing the prognostic value of UCA1 in digestive system carcinomas." (PMID 28380443, 2017). "UCA1 may serve as a novel biomarker for predicting the prognosis and assessing clinicopathologic features in digestive system carcinomas." (PMID 28380443, 2017). "In addition, many studies suggested that the expression of UCA1 was also related to prognosis of digestive system carcinomas." (PMID 28380443, 2017). "In conclusion, the meta-analysis results of this study could help to improve our understanding on the prognosis significance of UCA1 in different types of digestive system carcinomas." (PMID 28380443, 2017). "Taken together, the results above showed that UCA1 overexpression was significantly correlated with LNM and DM in digestive system cancer patients, suggesting that UCA1 may serve as an indicator for metastasis of digestive system malignancies." (PMID 28074092, 2016). "In subgroup analysis for OS, UCA1 at high level in cancerous tissues may be a reliable prognostic marker specifically for digestive system cancers." (PMID 27517147, 2016). "A meta-analysis showed that high expression of UCA1 is significantly associated with poorer OS and DFS in patients with digestive system cancers, including CRC, suggesting that UCA1 could serve as an prognostic factor for predicting clinical outcome for patients with digestive system cancers." (PMID 31480503, 2019).
adenocarcinoma (1 paper, 2024). A common cancer characterized by the presence of malignant glandular cells. "The regulatory purpose of UCA1 In CC was studied by several groups, the majority of which examined its effects in the adenocarcinoma representative HeLa cells." (PMID 38534790, 2024). "Furthermore, the adenocarcinoma and non-adenocarcinoma tissue types I and II, predominantly the lymph node metastasis specimens, exhibited considerably elevated UCA1 expression." (PMID 38534790, 2024). "The analysis of tissue specimens from both studies revealed significant upregulation of UCA1 in adenocarcinoma, including endometrioid, and non-adenocarcinoma tissues compared to normal samples." (PMID 38534790, 2024).
bone disorder (1 paper, 2024). "Recently, UCA1 has been linked to bone development and remodeling, suggesting it could be a target for treating various bone disorders." (PMID 39156986, 2024). "Targeting UCA1 for bone disorders presents a number of challenges, including the necessity for effective delivery mechanisms, off-target effects brought on by its involvement in numerous cellular processes, and potential individual differences in expression levels." (PMID 39156986, 2024).
digestive system tumors (1 paper, 2017). "It would further support UCA1 as a promising biomarker for the prognosis of digestive system tumors." (PMID 28380443, 2017). "But the prognostic value of UCA1 in the malignant digestive system tumors was still not clear." (PMID 28380443, 2017).
genetic disorders (1 paper, 2020). "CRC onset was implied as the comprehensive outcome of genetic disorders and exposure to hazardous surroundings, and here we attempted to clarify the interactive role of SNPs in UCA1 and environmental risks in enhancing CRC risk." (PMID 32143722, 2020).
heart diseases (1 paper, 2016). "In normal states, UCA1 is specifically expressed in heart of adult, indicating that UCA1 might be as a biomarker for heart diseases such as AMI." (PMID 26949706, 2016).
immune dysfunction (1 paper, 2016). "Furthermore, UCA1 is also expressed in the spleen in normal states, indicating that the level might be changed with immune dysfunction." (PMID 26949706, 2016).
UCA1 also shares sentences with these, for which no sentence is quoted: acute myocardial infarction (3 papers); heart failure (2); Hypertension (2); lung squamous cell carcinoma (2); Oral Cancer (2); pituitary cancer (2); acute lymphoblastic leukemia (1); anaplastic gliomas (1); aortic aneurysm (1); atopic dermatitis (1); autoimmune disease (1); benign breast diseases (1); bile duct carcinoma (1); chronic pancreatitis (1); COVID-19 (1); diabetic nephropathy (1); endometrial polyp (1); endometrioid adenocarcinoma (1); heart (1); hyperlipidemia (1); hypopharyngeal squamous cell carcinoma (1); intrauterine growth retardation (1); ischemia reperfusion injury (1); ischemic stroke (1); kidney cancer (1); kidney damage (1); lung injury (1); medulloblastoma (1); mucinous cystadenocarcinoma (1); myocardial ischemia (1).
A further 14 diseases each share a sentence with UCA1 in 1 paper.